CRP (C-reactive protein)
Diseases named in the same sentence as CRP in open-access papers (continued):
Sharing a sentence is not in itself a finding about the gene and the disease.
cancer (continued). "Therefore, we speculate that GPS might be a better predictor of the prognosis of cancer than CRP." (PMID 28008988, 2016). "The crude model included the following variables: male gender, history of cancer, history of HTN, BUN, MCV, sodium, CRP, and ESR." (PMID 27267984, 2016). "In the case of CRP, the impact of childhood trauma on adulthood inflammation may be characterised by synergistic effects with the presence of ‘state‘ (current) ill health, as the effect sizes were significantly greater in clinical samples, including patients with cancer." (PMID 26033244, 2016). "Recently, hematological markers of systemic inflammation, such as NLR, C-reactive protein (CRP), and platelet to lymphocyte ratio (PLR), have been shown to have prognostic value in cancer patients." (PMID 26843858, 2016). "There is now accumulating evidence that the markers of the systemic inflammatory response, including cytokines, C-reactive protein (CRP), albumin, serum amyloid A and white cell count, can be independent prognostic factors in cancer patients." (PMID 27136467, 2016). "Recently, inflammation has been widely recognized to contribute to cancer progression and various inflammatory markers, such as the NLR, CRP, GPS and mGPS have been reported to be correlated with the survival of patients with CRC." (PMID 27812440, 2016). "The marked difference in OS for high versus low IL-6 or CRP despite relatively small differences in PFS is consistent with data indicating a special role of inflammation in advanced and cachectic cancer." (PMID 27738330, 2016). "In the univariate analyses, male gender; history of cancer, HTN, and chronic pulmonary disease; and BUN, Hb, MCV, WBC, sodium, CRP, and ESR values all showed statistically significant associations with in-hospital mortality." (PMID 27267984, 2016). "A growing body of studies suggests that NF-kB activation mediates up-regulation of inflammatory cytokines, angiogenic factors (e.g. CRP, IL-6, TNF-α, IL-1β, VEGF, MMP-9) in cancer." (PMID 26192925, 2015). "Positive correlations (|r|>0.45) among CRP, IL-6, TNF-α, IL-1β, MMP-9, VEGF, and TF antigen were found in both groups of cancer patients, whereas the fibrinogen correlated only in DVT+ group." (PMID 26192925, 2015). "In conclusion we present CRP serum levels as a novel independent prognostic parameter in women diagnosed with ULMS, a rare cancer type vastly distinctive from both epithelial gynaecologic malignancies and other STS." (PMID 26248232, 2015). "They included 10 studies (n = 4502) and compared OS, cancer-specific survival, and DFS in patients with raised and low level of CRP." (PMID 26693355, 2015). "There is now good evidence that markers of the systemic inflammatory response, namely C-reactive protein and albumin using standard thresholds (termed the Glasgow Prognostic Score, GPS) have independent prognostic value in patients with a variety of cancers." (PMID 25730322, 2015). "CRP, serum ALB, and peripheral lymphocyte count in cancer patients have recently attracted research attention." (PMID 25022764, 2014). "The strongest overexpressed proteins in treated Caco-2 exosomes (eg, CD59, CRP, CTSD, HMMR, TRIM22) are involved as potential oncogenes in the pathogenesis of different cancers, including CRC." (PMID 25594007, 2014). "When comparing the impact of the different biomarkers on outcomes, CRP and GDF-15 were the only biomarkers related to cancer morbidity and mortality." (PMID 24312445, 2013). "The Kaplan-Meier 5-year cancer specific survival (CSS) rates were 54.2 and 26.4% for patients with preoperative CRP levels ≤ and >5 mg/l, respectively (p<0.006)." (PMID 23497335, 2013). "C-reactive protein (CRP) is an acute-phase reactant that is elevated during bacterial infection, inflammatory disease, trauma, surgery, and cancer." (PMID 23642165, 2013).
cancer (continued). "There is a growing area of research asserting that cancer- and cancer-treatment related fatigue is driven by pro-inflammatory cytokines (e.g., IL-6, IL-1β, TNF-α) and inflammatory pathways (e.g., CRP, IL-1RA) as observed using animal and clinical models." (PMID 23959120, 2013). "Twenty-eight out of forty-five subjects in our study had sharply elevated CRP levels (above 10 mg/L) prior to IVC therapy, suggesting that inflammation is a prevalent problem for cancer patients." (PMID 22963460, 2012). "Patients with an elevated C-reactive protein, adjusted calcium, Alk phos and GGT levels or low albumin levels were more likely to have cancer (all P<0.001)." (PMID 20717110, 2010). "Among them, inflammatory markers, especially C-reactive protein (CRP), have been suggested to predict survival in different cancers, including NSCLC." (PMID 20234363, 2010). "However, CRP is a nonspecific marker of inflammation, and additional studies of specific cytokines that regulate acute-phase response are necessary to elucidate the mechanisms by which inflammation influences the risk of cancer." (PMID 20673375, 2010). "We were unable to establish any links between CRP level and change in FFM in any of our advanced cancer groups over the course of chemotherapy." (PMID 15726121, 2005). "C-reactive protein, interleukin-6, soluble gp130, soluble TNF receptor, interleukin-1 receptor antagonist and IL-8 concentrations were significantly elevated in cancer patients (P⩽0.001)." (PMID 15570310, 2004). "C-reactive protein (CRP), an inflammation marker and acute-phase protein produced in response to inflammation, is correlated with tumor progression and prognosis in several cancers, including PCa 31-33." (PMID 41583511, 2026). "The CRP–Albumin–Lymphocyte (CALLY) index is a composite prognostic marker incorporating C-reactive protein (CRP), albumin, and lymphocyte count, reflecting systemic inflammation, nutritional status, and immune function in cancer patients." (PMID 40836295, 2025). "However, stratification analysis indicated that the CRP rs1205 C>T polymorphism was correlated with an increased risk of cancer in Asians, but not in European populations, suggesting that the relationship between CRP-related SNPs and CRC susceptibility may vary by ethnicity." (PMID 39980561, 2025). "Additionally, chemotherapy patients showed increased inflammatory markers (e.g., IL-6, CRP) in CRC, which correlate with reduced survival and worse cancer health outcomes." (PMID 40862807, 2025). "In terms of laboratory findings, the CRP level in the cancer group was greater than that in the noncancer group." (PMID 40241057, 2025). "Systemic inflammation, reflected in biomarkers like the high-sensitivity C-reactive protein-to-albumin ratio (HAR), fibrinogen (FIB), and hemoglobin (HB), has emerged as a key player in cancer progression, yet its integration into clinical predictive tools remains underexplored." (PMID 41142623, 2025). "Evidence indicates that inflammatory markers, including C reactive protein (CRP), interleukin-6 (IL-6), systemic inflammatory response index (SII), and neutrophil-to-lymphocyte ratio (NLR), are critical factors influencing cancer prognosis." (PMID 40313883, 2025). "Third, Numerous studies have demonstrated that conventional inflammatory markers, such as the neutrophil-lymphocyte ratio (NLR), platelet-lymphocyte ratio (PLR), and C-reactive protein (CRP), possess strong prognostic predictive capabilities in cancer patients." (PMID 40365348, 2025). "The present study showed that the novel rapid salivary test kit could significantly differentiate between the salivary CRP values of healthy controls and those of OPMD and malignancy patients." (PMID 39851610, 2025). "In a meta-analysis including 6124 patients, elevated baseline CRP levels consistently predicted poorer survival outcomes, regardless of cancer type or the specific ICI used." (PMID 41009716, 2025).
cancer (continued). "Serum inflammatory markers and indices based on circulating immune cells and other laboratory values such as C-reactive protein (CRP) or lactate dehydrogenase (LDH) have been proposed as additional tools to predict response to treatment and clinical outcomes in various cancer types." (PMID 40102864, 2025). "Similarly, ratios combining different biomarkers, including the C‐reactive protein (CRP)‐albumin ratio (CAR), neutrophil‐to‐lymphocyte ratio (NLR), and platelet‐to‐lymphocyte ratio (PLR), have been proposed in an attempt to improve cancer prognostication." (PMID 40528380, 2025). "Similarly, in our study, we combined CRP with nutritional indicators such as BMI and albumin to create NCR, which has been shown to outperform CRP alone in predicting the prognosis of cancer cachexia." (PMID 40133874, 2025). "Several systematic reviews have also highlighted the link between inflammation and AF development in cancer patients, yet no study has specifically examined the correlation between CRP and new-onset AF in CSs." (PMID 41387931, 2025). "The novel CRP PPIs and the potential impact of CRP on specific GAG biosynthetic processes and glycoprotein production as it may relate to cancer is summarized below." (PMID 41614767, 2025). "Similarly, these sensors have been employed for protein and antigen detection, including key disease markers like C-reactive protein (CRP), prostate-specific antigen (PSA), and troponin, enhancing the early diagnosis of cardiovascular diseases and cancer." (PMID 40731657, 2025). "In univariate analysis, the following variables were associated with non-VAP: gender male, increase in CRP > 30% in 5 days, increase of WBC count over 30% in 5 days, ventilation days, SAPS2, cancer, bacterial colonization of the pharynx." (PMID 40177646, 2025). "In general, CRP is a non-specific acute-phase protein, which is often elevated in patients with cancer, sometimes even to levels similar to those in the patients in our study." (PMID 40596935, 2025). "In addition, during CRT, the patient's C-reactive protein (CRP) levels consistently exceeded 0.5 mg/dL, meeting the inflammatory criterion for cancer cachexia defined by the AWGC." (PMID 40539144, 2025). "CRP was the representative serum inflammatory marker, and LDH and ALP were also suggested as general surrogate tumor markers in PCa as well as the other types of malignant tumors." (PMID 40788408, 2025). "This aligns with findings from a network meta-analysis in cancer patients showing that combined aerobic and resistance training was superior to single-modality exercise in reducing inflammatory markers such as IL-6, IL-8, IL-10, TNF-α, and CRP." (PMID 41583457, 2025). "A recent study highlighted the importance of a hyperactive inflammatory response present in cancer patients, suggesting that a prognostic score, which includes NLR, PLR, C-reactive protein, and mGPS, could be used to assess the outcome of most cancers." (PMID 40282925, 2025). "In cancer patients, elevated BNP levels can occur without clinical heart failure, correlating with high-sensitivity C-reactive protein (hs-CRP) and reflecting cancer-associated inflammation." (PMID 39583604, 2024). "Other biomarkers, such as C-reactive protein (CRP), lactate, fibrinogen, D-dimer, and procalcitonin, did not significantly differ between the patients with and without cancer." (PMID 38225613, 2024). "H3Cit-DNA, cfDNA, NE and CRP were significantly higher in patients with cancer compared to patients without cancer (p < 0.0001, p < 0.0001, p = 0.004, and p = 0.0002 respectively)." (PMID 38941006, 2024). "Of note, most clinical trials that tested protocols based on procalcitonin or CRP to guide antibiotic therapy did not include cancer patients, especially if they were undergoing chemotherapy or were neutropenic." (PMID 39272020, 2024).
cancer (continued). "The ORs of NC, MC, WBC, CRP, PCT, PLR and SII for high-grade cancer stage were 1.12 (95%CI, 1.02–1.23), 4.20 (95%CI, 1.66–10.65), 1.21 (95%CI, 1.10–1.33), 1.07 (95%CI, 1.02–1.11), 1.40 (95%CI, 1.15–1.70), 1.25 (95%CI, 1.04–1.51) and 1.40 (95%CI, 1.15–1.70), sequentially (P < 0.05)." (PMID 39020272, 2024). "The link between MMP9 and inflammation is evident from its correlation with inflammatory mediators like IL-6 and CRP, indicating an inflammatory environment that may boost MMP9 levels, thereby facilitating cancer’s advancement." (PMID 39664453, 2024). "Of note, this chronic phlogistic state has been also observed in clinical practice and reported in the literature, with the help of serum inflammatory markers such as C-reactive protein (CRP) and proinflammatory cytokines such as interleukin 6 (IL-6) in both cancer and HF." (PMID 38397436, 2024). "Regarding preoperative blood results the cancer patients and especially PDAC (PER+) show lower hemoglobin levels (PDAC (PER+) 10.8 g/dl vs. NC 14.2 g/dl) (p = 0.021), higher CRP (p = 0.01), bilirubin (p = 0.008) and gamma-glutamyl transferase (ɤGT) levels (p = 0.02)." (PMID 38846943, 2024). "CRP/PNI, an objective inflammatory index, has been reported in cancer populations." (PMID 38376000, 2024). "Serum C-reactive protein (CRP) was assessed in cancer patients as a non-specific marker of inflammation." (PMID 39199673, 2024). "It is possible that that cancer indirectly increases several parameters, such as NLR, D-Dimer, and CRP, resulting in the cancer variable not being significant during analysis." (PMID 38792539, 2024). "Proliferation marker Ki67 was in positive correlation with cancer stage and CRP but in negative correlation with red blood cells (RBCs), hematocrit, hemoglobin, MCHC, and alanine transaminase (ALT)." (PMID 39337548, 2024). "Our group has previously explored the prognostic role of several biomarkers of systemic inflammation, including c‐Reactive Protein (CRP), albumin, white cell count (WCC) neutrophil count (NC), in patients presenting with malignancy of undefined primary origin MUO or CUP to a single cancer centre." (PMID 38404120, 2024). "Although previous studies have reported chemotherapy-induced inflammation in cancer patients, we did not observe any significant interaction between chemotherapy use and CRP levels, probably due to low statistical power." (PMID 38613909, 2024). "CRP is possibly an active mediator of cancer progression and aggressive phenotype, rather than merely a passive reflection of the inflammatory process." (PMID 39010859, 2024). "CRP is a marker of inflammatory response and the reduction of CRP in the FMD group can reduce chronic inflammation, oxidative stress, and ultimately reduce the progression of cancer cells." (PMID 39703333, 2024). "Recently, numerous useful prognostic biomarkers in different types of cancer, including CRC, have been reported by combining these individual markers, such as the lymphocyte‐to‐CRP ratio, CRP‐to‐albumin ratio, neutrophil‐to‐lymphocyte ratio, and platelet‐to‐lymphocyte ratio." (PMID 39229558, 2024). "We tested the relationship between serum CRP levels and CD64 expression in cancer tissues." (PMID 39564003, 2024). "CRP measurement has now been incorporated into UK guidance for minimum datasets in patients with cancer but has not yet been formally included in guidelines for assessing patients with cCUP or MUO." (PMID 38404120, 2024). "C-reactive protein (CRP) has gained prominence as a tool for monitoring therapeutic responses and reducing the duration of antibiotic therapy; however, few studies have analyzed this protein in cancer patient populations." (PMID 39272020, 2024). "The NUn score, which incorporates CRP and ALB levels and WBC counts, effectively captures the key aspects of systemic inflammation and nutritional status, which are both critical determinants of cancer progression and patient outcomes." (PMID 39513125, 2024).
cancer (continued). "Although a high C-reactive protein-to-albumin ratio (CAR) is believed to increase mortality risk, the association between the physical activity (PA), CAR, and mortality among cancer survivors has not been investigated." (PMID 39358685, 2024). "Cancer treatment resulted in an increase in prealbumin and albumin levels (p < 0.001) and a reduction in CRP levels (p < 0.001), with no change in UAMA (p = 1.000)." (PMID 39619813, 2024). "Sex, age, location, size, depth, pain due to the tumor, primary origin, serum C-reactive protein (CRP) level, MRI examinations, diagnosis by a previous physician, carcinoma markers from blood, history of carcinoma, other metastases, performance status (PS), and surgical procedures were documented." (PMID 38730358, 2024). "For instance, one might speculate that inflammation level (e.g., CRP, neutrophils, and NLR) might increase whereas albumin level might decrease following a cancer diagnosis, because of cancer biology, cancer treatment, or both." (PMID 37876941, 2023). "IMMUNEPOTENT CRP (ICRP) is an immunotherapy that has cytotoxic effects in several cancer cells without affecting peripheral blood mononuclear cells (PBMC) and CD3+ cells." (PMID 36998710, 2023). "Specifically, the variables in group 1 included gender, pulse, systolic pressure, leucocyte count, neutrophils count, lymphocyte count, neutrophil-to-lymphocyte ratio (NLR), c-reactive protein (CRP), procalcitonin(pct), albumin, urea nitrogen (BUN), D-dimer and cancer(p < 0.05)." (PMID 37528213, 2023). "But a limitation of this explorative study of the diagnostic utility of plasma CRP, IL‐6 and YKL‐40 in detection of cancer is the lack of a validation cohort." (PMID 36440611, 2023). "Hence, the correlation between TMMV and established predictive biomarkers of cancer cachexia, including IL-1, TNF-alpha, IL-6, CRP, and serum albumin, warrants investigation." (PMID 37959329, 2023). "Based on our observations, when encountering a covid-19 positive cancer patient in the ED with history of CHF, with an elevated CRP and/or PCT levels, has received chemotherapy within 1 month, and/ or is tachypneic (respiratory rate >22), one can objectively predict an increased risk of mortality." (PMID 36701309, 2023). "The proposed Inflammatory Prognostic Scale based on three parameters (CRP, LDH, and NLR) could prove to be useful for the timely introduction of modifications in the multidirectional comprehensive treatment of cancer." (PMID 36677048, 2023). "CRP is subject to regulation by key molecular triggers of cachexia, such as IL-6, IL-1β, and TNF-α, which not only promote cancer cell growth and safeguard cancer cells against apoptosis but also stimulate angiogenesis and metastasis." (PMID 37755304, 2023). "Furthermore, elevated ESR, CRP, and lactate dehydrogenase (LDH) levels have been identified as adverse prognostic factors impacting the survival of cancer patients." (PMID 37987280, 2023). "Our study highlighted that higher CRP values were found in diabetic cancer patients (average value 73.47 g/L) compared with non-diabetic patients (average CRP value 38.3 g/L)." (PMID 37627906, 2023). "In patients not diagnosed with cancer, CRP correlated with IL‐6 (r = 0.59) and YKL‐40 (r = 0.34), and IL‐6 with YKL‐40 (r = 0.54)." (PMID 36440611, 2023). "We hope that there will be a general awareness of suspicion of cancer in a subject with nonspecific symptoms of cancer and with high plasma CRP and no known inflammatory disease." (PMID 36440611, 2023). "Malignant neoplasms, DBBF, and chronic diseases involving the immune mechanism are three major diseases that may have direct effects on blood cell counts and CRP levels." (PMID 36855116, 2023). "We have previously shown that baseline CRP, with a cut‐off of 10 mg/L, is a very strong indicator for prognosis in ICI treated multiple advanced cancer types and the identification and validation of the CRP cut‐off is explained in detail in our previous publication." (PMID 37329173, 2023).